FAF2 (Fas associated factor family member 2)
Description:
Plays an important role in endoplasmic reticulum-associated degradation (ERAD) that mediates ubiquitin-dependent degradation of misfolded endoplasmic reticulum proteins. By controlling the steady-state expression of the IGF1R receptor, indirectly regulates the insulin-like growth factor receptor signaling pathway. Recruits ATPase VCP to lipid droplets and also binds to phospholipase PNPLA2/ATGL, inhibiting PNPLA2 activity by promoting its dissociation from its ABHD5/CGI-58 activator. This inhibits PNPLA2-mediated triacylglycerol hydrolysis and leads to inhibition of lipid droplet degradation. Involved in stress granule disassembly: associates with ubiquitinated G3BP1 in response to heat shock, thereby promoting interaction between ubiquitinated G3BP1 and VCP, followed by G3BP1 extraction from stress granules and stress granule disassembly.
Synonyms: ETEA; KIAA0887; UBXD8; UBXN3B
Tractability: Antibody: its Gene Ontology location is reachable by antibodies, with high confidence. PROTAC: ubiquitination databases record sites on it; its protein half-life has been measured.
Gene: Protein-coding gene on chromosome 5 (176,447,628 to 176,510,075, forward strand). Ensembl gene ENSG00000113194.
Subcellular location: Cytoplasm; Lipid droplet; Endoplasmic reticulum
Subcellular location (Human Protein Atlas): Lipid droplets; Endoplasmic reticulum
Pathways (Reactome):
Immune System: Neutrophil degranulation
Signal Transduction: RHOA GTPase cycle
Gene Ontology:
Molecular function: lipase binding; lipase inhibitor activity; protein binding; protein-macromolecule adaptor activity; ubiquitin binding; ubiquitin protein ligase binding
Biological process: ERAD pathway; lipid droplet organization; retrograde protein transport, ER to cytosol; stress granule disassembly; proteasomal protein catabolic process; proteasome-mediated ubiquitin-dependent protein catabolic process
Cellular component: endoplasmic reticulum; lipid droplet; VCP-NPL4-UFD1 AAA ATPase complex; ATPase complex; azurophil granule lumen; extracellular region; cytoplasm
Genetic constraint (gnomAD): Loss-of-function variants: 9 observed, 56.83 expected, observed/expected ratio (o/e) 0.16, 90% interval 0.094 to 0.28. The upper end of that interval is the gene's LOEUF score, 0.28, which puts it in group 1 of 6, group 1 being the genes least tolerant of losing a copy. Missense variants: 347 observed, 539.02 expected, observed/expected ratio (o/e) 0.64, 90% interval 0.59 to 0.7. Synonymous variants: 197 observed, 195.74 expected, observed/expected ratio (o/e) 1.01, 90% interval 0.89 to 1.13.
Homologues: Orthologues: dog FAF2 (99% identical), macaque FAF2 (99% identical), pig FAF2 (99% identical), rabbit FAF2 (99% identical), mouse Faf2 (98% identical), rat Faf2 (98% identical), chimpanzee FAF2 (96% identical), guinea pig FAF2 (93% identical), zebrafish faf2 (84% identical), tropical clawed frog faf2 (81% identical), Drosophila melanogaster Faf2 (45% identical), Caenorhabditis elegans H40L08.1 (17% identical). Paralogues in human: FAF1 (30% identical), UBXN7 (18% identical), UBXN8 (12% identical), UBXN10 (11% identical).
Diseases named in the same sentence as FAF2 in open-access papers:
FAF2 is named in the same sentence as 16 diseases in open-access papers, as found by Europe PMC text mining. Sharing a sentence is not in itself a finding about the gene and the disease. The quoted sentences say what the papers report.
steatosis (3 papers, 2015 to 2025). Increased lipid within the cytoplasm of cells. "Future research using additional animal models and FAF2-specific knockout mice is warranted to further elucidate the pathways by which FAF2 influences liver steatosis, supporting its potential as a therapeutic target for ALD." (PMID 39969435, 2025). "This reduction in SREBP1 and its downstream target genes likely contributes to the protective effect of Faf2 knockdown against alcohol-induced steatosis." (PMID 39969435, 2025). "Collectively, these results suggest that hepatic Faf2 knockdown may ameliorate alcohol-induced steatosis by enhancing lipolytic activity through increased ATGL transport to LDs and its activation by CGI-58 and ELMOD2." (PMID 39969435, 2025). "Targeted liver-specific knockdown of Faf2 in mice mitigated alcohol-induced steatosis." (PMID 39969435, 2025). "Thus, activating ATGL through FAF2 reduction in ALD-related steatosis may offer a promising therapeutic strategy." (PMID 39969435, 2025). "Our data suggest that FAF2 may regulate liver PCSK9 levels, potentially through the FOXO3-SIRT6 pathway, thereby contributing to the amelioration of ethanol-induced steatosis and the reduction in circulating LDL cholesterol." (PMID 39969435, 2025). "To date, no established connection exists between FAF2 and PCSK9 in the regulation of steatosis in ALD." (PMID 39969435, 2025).
Cirrhosis (2 papers, 2023 to 2025). A chronic disorder of the liver in which liver tissue becomes scarred and is partially replaced by regenerative nodules and fibrotic tissue resulting in loss of liver function. "A genome-wide association study and meta-analysis conducted by Schwantes-An et al12 identified a significant association between the Fas-Associated Factor Family Member 2 (Faf2) gene and the development of alcohol-associated cirrhosis." (PMID 39969435, 2025). "Interestingly, the majority of SNPs identified as risk factors for alcohol-associated cirrhosis in recent GWAS reside in/around the genes related to lipid metabolism and lipid droplet biology (PNPLA3, HSD17B13, FAF2 and TM6SF2)." (PMID 37887024, 2023).
pancreatic cancer (2 papers, 2021 to 2023). "on DEGs associated with lipid metabolism revealed that FAF2 was highly expressed in pancreatic cancer tissues and cells, and that abnormalities in lipid metabolism are an important ferroptosis-associated pathway, laying the foundations for this study." (PMID 38268915, 2023). "The mRNA expression levels of CSTF2, FAF2, KIF20B, AKR1A1, APOM, KRT6C, and CD70, which were included in the prognostic model, were detected in different types of pancreatic cancer cell lines." (PMID 38268915, 2023).
atopic dermatitis (1 paper, 2021). "Fas-associated factor family member 2 (FAF2) plays an important role in regulating the resistance to apoptosis observed in T cells and eosinophils from atopic dermatitis patients." (PMID 35082796, 2021).
breast carcinoma (1 paper, 2021). "Thus, it is not surprising that FAF2 and ERLIN2 have also been implicated in cancer, for example in uveal melanoma and breast cancer, respectively." (PMID 34406391, 2021).
Hepatic steatosis (1 paper, 2025). Steatosis is a term used to denote lipid accumulation within hepatocytes. "To investigate the molecular mechanisms underlying the effect of Faf2 knockdown on alcohol-induced liver steatosis, we performed RNA sequencing and bioinformatic analysis." (PMID 39969435, 2025). "Interestingly, knocking down FAF2 in the liver using adeno-associated virus serotype 8–delivered short hairpin RNA conferred a protective effect against alcohol-induced liver steatosis in ethanol-binged mice." (PMID 39969435, 2025). "Suppression of FAF2 expression alleviated alcohol-induced liver steatosis through ATGL activation and SREBP1 pathway, as well as reducing plasma LDL levels via the PCSK9 pathway." (PMID 39969435, 2025). "Understanding FAF2’s role in this context will provide insights into the molecular mechanisms driving hepatic steatosis, potentially informing the development of targeted therapies aimed at modulating FAF2 activity." (PMID 39969435, 2025). "Notably, Faf2 knockdown in ethanol-fed mice resulted in a marked reduction in hepatic steatosis, as evidenced by decreased intracellular LD accumulation in hematoxylin and eosin and Oil Red O staining." (PMID 39969435, 2025). "Our study demonstrated that Faf2 knockdown significantly reduced PCSK9 expression at both mRNA and protein levels, indicating that FAF2 may regulate PCSK9 expression and, thus, play a critical role in the development of liver steatosis." (PMID 39969435, 2025).
lung carcinoma (1 paper, 2021). "Orlistat induces ferroptosis in lung cancer cells (A549 and H1299) by repressing expression of Fas associated factor family member 2 (FAF2), a key factor regulating lipid droplet formation." (PMID 34742351, 2021).
proteinopathies (1 paper, 2022). "VCP and its adaptor FAF2 were recently found to mediate the extraction of G3BP1 from stress granules induced by heat stress, leading to their disassembly, which establishes an interesting connection between stress granule dynamics and the pathogenesis of proteinopathies." (PMID 35164882, 2022).
cancer (5 papers, 2021 to 2025). A tumor composed of atypical neoplastic, often pleomorphic cells that invade other tissues. "Fas-associated factor family member 2 (FAF2) is a molecule that regulates LD formation and in vivo balance and is downregulated during orlistat-induced ferroptosis in cancer cells, supporting the anti-ferroptosis effect of LD." (PMID 38509409, 2024). "As the coupling effect of SNHG6 was investigated in cancer cells, cholesterol availability sensed by FAF2 was hypothesized to crosstalk with LARS1, which senses leucine availability, in turn activating mTORC1 for downstream signaling pathway activation in diseased states, such as cancer." (PMID 37258576, 2023). "Among these genes, seven proteins (MAP2K1, FERMT2, HMGB2, FAF2, STK26, THRAP3, and KRT15) showed significant differences between carcinoma and adjacent tissues (TCGA-HNSC database)." (PMID 39319867, 2025). "For example, most cancer tissues exhibit weak to moderate cytoplasmic and/or nuclear immunoreactivity in the ASPSCR1, UBXN2A, UBXN10, UBXN1, FAF1, FAF2, UBXD2B proteins." (PMID 38365777, 2024).
tumor (3 papers, 2022 to 2024). "The role of FAF2 between ACC was the same as FAF1, and it was negatively associated with the stromal and immune score but positively associated with tumour purity." (PMID 38365777, 2024). "After tumor mutation profile and copy number variation (CNV) analyses, we established and validated a prediction model of KRAS mutations, based on survival analysis and mRNA expression, that contained seven genes: CSTF2, FAF2, KIF20B, AKR1A1, APOM, KRT6C, and CD70." (PMID 38268915, 2023).
FAF2 also shares sentences with these, for which no sentence is quoted: infection (2 papers); viral infection (2); amyotrophic lateral sclerosis (1); Arthritis (1); tauopathy (1); uveal melanoma (1).